IL12RB2 (interleukin 12 receptor subunit beta 2)
Description:
Receptor for interleukin-12. This subunit is the signaling component coupling to the JAK2/STAT4 pathway. Promotes the proliferation of T-cells as well as NK cells. Induces the promotion of T-cells towards the Th1 phenotype by strongly enhancing IFN-gamma production.
Tractability: Antibody: its Gene Ontology location is reachable by antibodies, with high confidence; UniProt predicts a signal peptide or a membrane-spanning region; the Human Protein Atlas places it where antibodies can reach. PROTAC: ubiquitination databases record sites on it.
Gene: Protein-coding gene on chromosome 1 (67,307,364 to 67,398,724, forward strand). Ensembl gene ENSG00000081985.
Subcellular location: Membrane
Subcellular location (Human Protein Atlas): Plasma membrane
Pathways (Reactome):
Immune System: Interleukin-12 signaling; Interleukin-35 Signalling
Developmental Biology: Differentiation of naive CD4+ T cells to T helper 1 cells (Th1 cells)
Gene Ontology:
Molecular function: coreceptor activity; cytokine binding; cytokine receptor activity; protein kinase binding
Biological process: interleukin-12-mediated signaling pathway; positive regulation of type II interferon production; cell surface receptor signaling pathway; cytokine-mediated signaling pathway; negative regulation of T-helper 1 type immune response; positive regulation of cell population proliferation; regulation of B cell proliferation; response to cytokine
Cellular component: external side of plasma membrane; plasma membrane; receptor complex; membrane
Genetic constraint (gnomAD): Loss-of-function variants: 28 observed, 37.89 expected, observed/expected ratio (o/e) 0.74, 90% interval 0.55 to 1.01. The upper end of that interval is the gene's LOEUF score, 1.01, which puts it in group 4 of 6, group 1 being the genes least tolerant of losing a copy. Missense variants: 468 observed, 551.25 expected, observed/expected ratio (o/e) 0.85, 90% interval 0.79 to 0.92. Synonymous variants: 183 observed, 200.82 expected, observed/expected ratio (o/e) 0.91, 90% interval 0.81 to 1.03.
Homologues: Orthologues: chimpanzee IL12RB2 (99% identical), macaque IL12RB2 (94% identical), pig IL12RB2 (78% identical), dog IL12RB2 (77% identical), rabbit IL12RB2 (71% identical), mouse Il12rb2 (67% identical), rat Il12rb2 (65% identical), tropical clawed frog il12rb2 (27% identical), zebrafish il23r (13% identical). Paralogues in human: CSF3R (22% identical), LIFR (18% identical), IL6ST (17% identical), IL27RA (17% identical), OSMR (17% identical), IL31RA (14% identical), LEPR (12% identical), IL23R (10% identical), IL12RB1 (10% identical), PRLR (10% identical), IL6R (9% identical), CRLF1 (9% identical), and 11 more.
Diseases named in the same sentence as IL12RB2 in open-access papers:
IL12RB2 is named in the same sentence as 99 diseases in open-access papers, as found by Europe PMC text mining. Sharing a sentence is not in itself a finding about the gene and the disease. The quoted sentences say what the papers report.
Autoimmunity (8 papers, 2014 to 2023). The occurrence of an immune reaction against the organism's own cells or tissues. "In addition, IL-12Rβ2 plays immunosuppressive functions as IL-35 since IL-12Rβ2 deficiency leads to autoimmunity." (PMID 34622804, 2021). "Interestingly, the IL12RB2 rs3790558 SNP is a strong candidate for autoimmune disorders as this SNP has been previously implicated in autoimmune disorders such as systemic sclerosis." (PMID 31649612, 2019). "While the relevance of increases in the IL-12Rβ2 : IL-12Rβ1 receptor chain ratio to prevention of autoimmune responses remains to be established, IL-12Rβ2 has been shown to offer protection against both spontaneous autoimmunity and malignancy in murine models." (PMID 37957274, 2023). "A study found that IL12RB2 knockout (KO) mice develop autoimmunity, lymphoid proliferation, and B-cell tumors and suggested IL12RB2 functions physiologically in inhibiting aberrant B-cell activation." (PMID 35517856, 2022). "This DC-induced IL-12Rβ2-expressing Treg subpopulation may have a therapeutic advantage in suppressing Th1 mediated autoimmunity." (PMID 26745371, 2016). "Not surprisingly, therefore, IL-12Rβ2 has been shown to offer protection against both spontaneous autoimmunity and malignancy in murine models." (PMID 37957274, 2023).
autoimmune disease (6 papers, 2012 to 2025). A disorder resulting from loss of function or tissue destruction of an organ or multiple organs, arising from humoral or cellular immune responses of the individual to their own tissue constituents. "The receptors for IL-35, IL-12Rβ2 and gp130, have been implicated in the inflammatory pathophysiology of autoimmune diseases." (PMID 34149710, 2021). "The up-regulation of the IL12RB2 gene is associated with a number of infectious and autoimmune diseases." (PMID 23152861, 2012). "Genes related to these autoimmune diseases and Th17 cell differentiation, including CTLA4, IFN-ALPHA-8, IL12RB2, TRAV3, TRAV16, FOS, and VEGFA, were up-regulated in the E. coli group but down-regulated in the BL + E." (PMID 39707535, 2024). "Our study did not detect an association of previously identified autoimmune disease risk SNPs (rs2358817 within VTCN1 gene; rs1049550 within ANXA11 gene; rs6679356 within IL12RB2 gene andrs9865818 within LPP gene) with T1DM in Croatian T1DM trio families." (PMID 23152861, 2012).
Behcet disease (6 papers, 2013 to 2022). A chronic, relapsing, multisystemic vasculitis characterized by mucocutaneous lesions, as well as articular, vascular, ocular and central nervous system manifestations. "Additionally, several SNPs (such as rs12119179, rs1495965, and rs924080) near the IL12RB2 gene were found to be associated with Behcet's disease in genome-wide association studies, were the disease can lead to inflammation in the brain and central nervous system." (PMID 31649612, 2019).
lung carcinoma (6 papers, 2017 to 2025). "Analyses of public databases revealed that high levels of IL12RB2 in cancer samples were associated with worse survival of lung cancer patients." (PMID 30218063, 2018). "In a lung cancer transplant model assay, it was observed that mice lacking IL12RB2 developed lung adenocarcinoma." (PMID 37762335, 2023). "In lung cancer cell lines that are negative for IL12RB2, use of the demethylating agent 5-aza-deoxycytidine was able to restore expression of the receptor." (PMID 33092094, 2020).
primary biliary cirrhosis (6 papers, 2012 to 2020). "IL12RB2 constitute a risk factor for primary biliary cirrhosis, with the reported top associated SNPs mainly located in intronic sequences." (PMID 24151497, 2013). "A GWAS of 2072 North American patients identified 16 SNPs associated with PBC with the strongest association at the HLA-DQB1 locus as well as SNPs at IL12A and IL12RB2, implying a role for interleukin-12 in the development of primary biliary cirrhosis." (PMID 33202590, 2020). "Genetic research of primary biliary cirrhosis (PBC) showed significant association of rs6679356 within the interleukin 12 receptor, beta 2 (IL12RB2) gene." (PMID 23152861, 2012). "Notably, a recent GWA study of primary biliary cirrhosis revealed an association with IL12RB2, IL12A (a gene encoding for the p35 subunit of the IL-12 cytokines) and STAT4 (downstream of IL12RB2)." (PMID 24586521, 2014).
breast carcinoma (5 papers, 2014 to 2023). "Both STAT3 and STAT4 were responsible for the transcription of IL12RB1 and IL12RB2 in breast cancer cell." (PMID 38107057, 2023). "The expression of IL12Rβ2 was higher in the metastatic tumors in head and neck cancers as well as breast cancers, and the effect was more prominent in early breast cancers." (PMID 30218063, 2018). "Moreover, we performed IHC to analyze the expression of IL12Rβ2 in paired primary-metastatic tumor samples, including 10 paired head and neck cancers and 37 paired breast cancers." (PMID 30218063, 2018). "Also, a large-scale analysis for screening 3,144 SNPs from 156 breast cancer patients has revealed that ABCA1 and IL12RB2 polymorphism are highly susceptible to radiation-induced dermatitis." (PMID 24594932, 2014). "Therefore, IL12RB2 may affect breast cancer development by regulating Th17 cells." (PMID 36911413, 2023). "Bioinformatic analysis in breast cancer has shown that high expression of IL-12/STAT4 axis molecules, such as the IL-12 receptor genes (IL-12RB1 and IL-12RB2), STAT4, IFNγ, and TBX21, significantly increases the survival rates of patients with breast cancer, especially the more aggressive subtypes." (PMID 33076315, 2020).
lung adenocarcinoma (5 papers, 2009 to 2025). A carcinoma that arises from the lung and is characterized by the presence of malignant glandular epithelial cells. "In the reverse MR analyses, AGRN and IL12RB2 demonstrated potential reverse causal effects, suggesting that genetic liability to lung adenocarcinoma and small cell carcinoma, respectively, may influence circulating levels of these proteins." (PMID 41340014, 2025). "We first investigated the expression of the IL-12Rβ2 in lung tissue samples from seventy lung adenocarcinoma patients." (PMID 19582164, 2009). "Stage I lung adenocarcinomas showed significantly (P = 0.012) higher frequency of IL-12Rβ2 expressing samples than stage II/III tumors." (PMID 19582164, 2009). "IL12RB2 and TNFRSF8 are associated with the risk of lung adenocarcinoma." (PMID 37332770, 2023). "Since alveolar and bronchiolar epithelium surrounding the neoplastic tissue from lung adenocarcinoma patients expressed IL-12Rβ2, we next investigated whether IL-12Rβ2 was expressed and functional in NBEC from patients undergoing lung resection for non-malignant disorders." (PMID 19582164, 2009). "In principle, IL-12 might be administered to lung adenocarcinoma patients (selected on the ground of IL-12Rβ2 expression in tumor cells) as tumor-targeted formulations to act directly on the tumor microenvironment or systemically to take advantage of the immunomodulatory activity of the cytokine." (PMID 19582164, 2009). "Using tissue microarray and immunohistochemistry, Suzuki and colleagues found that tumor interleukin-12 receptor β2 (IL-12Rβ2), IL-7R, and stromal FoxP3/CD3 ratio are independent predictors of recurrence in patients with stage I lung adenocarcinoma." (PMID 25950176, 2015). "When only IL-12Rβ2 positive and negative lung adenocarcinomas according to the score used were analyzed, IL-12Rβ2 positive tumors were significantly more numerous in stage I than stage II/III patients (P = 0.012, Fisher's exact test)." (PMID 19582164, 2009). "Immunohistochemical analyses revealed that 29/70 lung adenocarcinomas (41.4%), 22/49 of which were adenocarcinomas with bronchioloalveolar features (ADBF), 4/13 pure bronchioloalveolar carcinomas (BAC) and 3/8 conventional adenocarcinomas (ADC), did not express IL-12Rβ2." (PMID 19582164, 2009).
psoriasis (5 papers, 2009 to 2023). An autoimmune condition characterized by red, well-delineated plaques with silvery scales that are usually on the extensor surfaces and scalp. "This is because IL-12p35- or IL-12Rβ2-deficient mice showed exacerbated psoriasis compared to WT mice, indicating that IL-12 protects from psoriasis skin inflammation." (PMID 33664371, 2021). "The highest increase of Il12rb2 (IL-23 receptor β chain) in Pla2g2a−/− mice relative to Pla2g2a+/+ mice might be a reflection of the increased Th17-type immunity, which could be associated with psoriasis in distal skin." (PMID 35076024, 2022). "Independent associations of psoriasis and psoriatic arthritis with both IL23R and a SNP 4 kb upstream of IL12RB2, indicate that extended studies in this gene cluster would be relevant to other chronic inflammatory diseases as well." (PMID 19175939, 2009). "Some polymorphisms identified in genes such as TNF, IL12RB2, and IL12B could be also involved in the production, differentiation, or activity of Tregs, pointing to a genetic background of Treg dysfunction in psoriasis." (PMID 37628670, 2023). "Hallmark pathways of psoriasis were analysed and among the cytokines IL-17A and IL-17F were elevated in the absence of IL-12Rβ2." (PMID 27892456, 2016). "Future studies employing a tagging strategy of the whole IL12RB2 gene may be useful in IBD, psoriasis and celiac disease." (PMID 19175939, 2009).
chronic obstructive pulmonary disease (4 papers, 2014 to 2023). A chronic and progressive lung disorder characterized by the loss of elasticity of the bronchial tree and the air sacs, destruction of the air sacs wall, thickening of the bronchial wall, and mucous accumulation in the bronchial tree. "Furthermore, IL12RB2 methylation has been found to be frequent in patients suffering from both chronic obstructive pulmonary diseases (COPD) and non-small-cell lung cancer (NSCLC)." (PMID 36766706, 2023). "However, in mouse model of chronic obstructive pulmonary disease (COPD), challenge with S. aureus or Haemophilis influenzae lead to loss of GATA-3 expression in ILC2 and a subsequent increase in the expression of IL-12Rβ2, IL-18Rα, and T-bet giving them an ILC1-like phenotype." (PMID 31781103, 2019).
colitis (4 papers, 2021 to 2025). Inflammation of the colon. "In contrast, Il12rb2−/− mice displayed significantly attenuated C. rodentium–induced colitis, associated with a less evident accumulation of proinflammatory immune subsets and less severe microstructural alterations in the distal colon following C. rodentium infection." (PMID 38498592, 2024). "The findings of the current study indicated that murine hosts lacking the IL-12/IL-12Rβ2 axis downstream of IL-21/IL-21R signaling and their littermate controls were equally susceptible to colon infection, yet Il12rb2−/− mice exhibited attenuated C. rodentium–induced colitis." (PMID 38498592, 2024). "Genetic deletion of the IL-12Rβ2 signaling pathway led to the attenuation of C. rodentium–induced colitis in vivo." (PMID 38498592, 2024). "While the cascade of events leading to the activation of STAT3 by IL-21 has been extensively studied, it is unclear how the events downstream of IL-12Rβ2 signaling affect the expression of proinflammatory gene profiles during colitis." (PMID 38498592, 2024). "Specifically, it was found that the expression of Ifng, Il12rb1, and Il12rb2 was impaired in colonic CD4+ T cells of Il21r−/− mice during C. rodentium–induced colitis." (PMID 38498592, 2024). "Further studies are required to identify the exact contribution of IL-12Rβ1 and IL-12Rβ2 in mediating the proinflammatory functions of IL-21/IL-21R signaling during colitis." (PMID 38498592, 2024). "In this study, a previously less-defined function of the IL-21/IL-21R signaling in the regulation of colitis through interaction with the IL-12/IL-12Rβ2 signaling was identified." (PMID 38498592, 2024). "The effect of the Il12rb2 genetic ablation on the outcome of C. rodentium–induced colitis in Il12rb2−/− mice and their Il12rb2+/+ littermates was further studied." (PMID 38498592, 2024). "Consistently, these findings also point to an indispensable role of the IL-12Rβ2 signaling axis in promoting proinflammatory immune responses during Citrobacter rodentium–induced colitis." (PMID 38498592, 2024). "The findings of the current study provide novel insights into the mechanisms by which functional IL-21/IL-21R signaling regulates IL-12 responsiveness by promoting IL-12Rβ2 expression in CD4+ T cells, leading to colitis." (PMID 38498592, 2024). "The genetic ablation of IL-12Rβ2 led to the significant attenuation of colitis, despite its nonessential roles in eradicating C. rodentium infection in vivo." (PMID 38498592, 2024). "Mice lacking functional IL-12Rβ2 signaling exhibited attenuated colitis following C. rodentium infection, whereas the ability of those mice to effectively eradicate C. rodentium infection was unaffected." (PMID 38498592, 2024). "Collectively, these findings indicated a novel and previously unknown role played by IL-21/IL-21R signaling in driving CD4+ T-cell responsiveness to IL-12 by enhancing the expression of IL-12Rβ2 in CD4+ T cells, thereby imprinting a TH1-biased immunity during bacterial-induced colitis." (PMID 38498592, 2024). "It was hypothesized that IL-21 would be required for the optimal expression of IL-12Rβ2, but not IL-12Rβ1, in CD4+ T cells, thereby regulating a TH1-biased immune profile following colon inflammation." (PMID 38498592, 2024).
laryngeal carcinoma (4 papers, 2022 to 2025). Carcinoma that arises from the laryngeal epithelium. "Higher expression of IL12RB2 was reported to be associated with better prognosis and longer survival in various human tumors, including lung and laryngeal cancers." (PMID 36694264, 2023). "IL12RB2 is a subunit of the IL-12 receptor, and an increased ratio of IL12RB2-positive tumor-infiltrating lymphocytes is indicative of a good prognosis in laryngeal cancer." (PMID 39282247, 2023). "IL12RB2 is one of the subunits of the interleukin-12 (IL-12) receptor and its abnormal expression is closely related to the prognosis of laryngeal cancer." (PMID 36518627, 2022).
leprosy (4 papers, 2008 to 2025). Leprosy is a chronic infectious disease affecting primarily the skin and peripheral nervous system. "RR specimens also expressed S100A12, which encodes an antimicrobial protein induced by TLR2/1L and IFN-γ in human macrophages, as well as IL12B and IL12RB2, known to be involved in host defense against leprosy." (PMID 40569678, 2025). "IL12RB2 has been associated with leprosy but not TB and, to our knowledge, IL12A has not been associated with TB in any study." (PMID 19116662, 2008).
melanoma (4 papers, 2014 to 2025). A malignant, usually aggressive tumor composed of atypical, neoplastic melanocytes. "The data suggest a model where overexpressing one component of the IL-12 receptor, IL12RB2, enables melanoma cells to shift the functional response via both IL-12-mediated and molecular crowding-based IL12RB2 homodimerization." (PMID 32450888, 2020). "To explore the generalizability of these results, we also found that the expression of IL12RB2:IL12RB1 is similarly skewed in human melanoma based on transcriptional profiles of melanoma cells and tumor-infiltrating lymphocytes." (PMID 32450888, 2020). "Nevertheless, we cannot discount the possibility that IK14004 may counter a tumour escape mechanism arising from expression of the IL-12 receptor chain, IL-12Rβ2, in murine melanoma cells." (PMID 40868162, 2025). "Some of these genes were also described in different works regarding UM, while two of them (CHL1 and IL12RB2) were also found to be hypermethylated with low expression in invasive malignant melanoma cells; in particular, CHL1 is in an hypermethylated region on 3p in TCGA class 2 UMs." (PMID 38339073, 2024). "Interestingly, the melanoma-related cell lines stained brightly for IL12RB2." (PMID 32450888, 2020). "In melanoma, overexpression of one component of the IL-12 receptor, IL12RB2, by malignant melanocytes may not only serve to deprive immune cells of this important cytokine, but malignant melanocytes may also use IL-12 as a means of activating cell survival pathways." (PMID 32450888, 2020). "The copy number of IL12RB2 was 1.5 times higher in the melanoma cell line versus the ‘normal’ melanocyte line, where the B16F0 cell line expressed over 330,000 copies of IL12RB2 and Melan-A cells had 214,000 copies." (PMID 32450888, 2020). "Following from this context, the mouse melanoma cell line B16F0 overexpresses one component of the IL-12 receptor, IL12RB2, to form a cytokine sink for IL-12, which can deprive neighboring immune cells of this important anti-tumor cytokine." (PMID 32450888, 2020). "In addition to secreting WISP1, B16 model for melanoma also overexpresses one component of the IL12 receptor, IL12Rβ2, that, in vitro, creates a local cytokine sink for IL12." (PMID 24426833, 2014).